HIF1A (hypoxia inducible factor 1 subunit alpha)
Diseases named in the same sentence as HIF1A in open-access papers (continued):
Sharing a sentence is not in itself a finding about the gene and the disease.
cancer (continued). "It stabilizes several cancer-related client proteins including PIM1, AKT, and HIF1A, which are crucial for tumor progression." (PMID 25167922, 2014). "Both HIF-1α and OATP were found to be highly expressed in canine and human cancer tissues in comparison with adjacent normal tissues." (PMID 25361418, 2014). "Further, HIF-1α and p-AMPKα were found to be upregulated in SDHB-silenced, but downregulated in SDHB-overexpressed cancer cells." (PMID 25491408, 2014). "In addition, inhibition of the PI3K/Akt pathway enhanced the therapeutic efficacy of paclitaxel in GC cells under hypoxic conditions, suggesting that the PI3K/Akt or HIF-1α pathway may serve as an important therapeutic target for the paclitaxel treatment of cancer." (PMID 24765145, 2014). "HIF-1α induces EMT and self-renewal of cancer stem cells, and facilitates metastasis; knockdown of HIF-1α inhibits or even reverses the EMT-like phenotype." (PMID 25566498, 2014). "The expression level of six differentially expressed mRNAs (CUL2, HIF1A, RET, JAK1, STAT1, and BCL2) in the cancer pathway and two of their nearby lncRNA pairs (RP11-124O11.2 and lincRNA-TMEM30B-1) was verified by real-time quantitative RT-PCR (qRT-PCR)." (PMID 24672800, 2014). "To select for cancer-marker-activated enzymes, we coexpressed the library of yCD-CH1 fusions along with the C-terminal activation domain (CTAD) of HIF-1α, which has been shown to interact strongly with the CH1 domain in E. coli." (PMID 25426963, 2014). "Besides exerting host immunosuppressive effects, hypoxia can lead to the development of aggressive cancer phenotypes such as cell immortalization, autocrine growth/survival, angiogenesis, invasion/metastasis, and resistance to chemotherapy, through a mechanism mediated mainly by HIF-1α." (PMID 23424623, 2013). "The regulation of the cellular stability and activity of HIF-1α and HIF-2α in normal cells and cancer cells is highly dependent on oxygen supply." (PMID 23301832, 2013). "At present, the in vivo study of the correlation between HIF-1α and MDR1/P-gp expression in human cancer cells remains limited." (PMID 23946810, 2013). "Therefore, Annexin A3 and HIF-1α have been hypothesized to be vital in the angiogenesis of cancer." (PMID 24260057, 2013). "We demonstrated that manipulating the dynamics of SEPT9_i1 filaments by FCF suppresses tumorigenic properties and downregulates both HIF-1α protein levels and HIF-1 transcriptional activity in cancer cells." (PMID 23977378, 2013). "Experimental evidence gathered in genetic mouse models over the past few years identified the transcription factor NF-κB, hypoxia inducible factor 1α (HIF-1α), and STAT-3 as the major molecular players linking inflammation and cancer." (PMID 23533994, 2013). "Everolimus reduces cellular proliferation, angiogenesis and glucose uptake via the inhibition of HIF-1α expression, which upregulates VEGF-mediated signal transduction in cancer cells." (PMID 23833638, 2013). "In the present study we examined VEGF and HIF-1α expression, and MVD via immunohistochemical analysis, in BRCA1-2 carriers and BRCAX cancer tissues." (PMID 23326384, 2013). "We examined expression of HIF-1α, c-Met, CA9, and GLUT1 in cervical neoplasias and cancer specimens by IHC." (PMID 23927384, 2013). "Many studies have shown that EGCG produces anti-cancer effect by modulating the activity of mitogen-activated protein kinases (MAPKs), IGF/IGF-1 receptor, Akt, NFκB and HIF-1α." (PMID 23638734, 2013). "The effect of FCF on HIF-1α protein level was checked in prostate (LNCaP), colon (HCT-116) and breast (MCF-7, MDA-MB-231) cancer cells." (PMID 23977378, 2013). "TTP also has multiple important targets, including COX-2, HIF-1α, IL-8, IL-6, IL-8, and VEGF 34,36–40 and the oncogenic Ser/Th kinase Pim-1, which is overexpressed in several cancers and promotes cellular growth and apoptosis resistance 41,42." (PMID 23401122, 2013).
cancer (continued). "It seems that baicalein inhibited cancer cell viability through the inhibition of cancer promoting genes expression including VEGF, HIF-1α, cMyc, and NFκB." (PMID 23502466, 2013). "The angiogenesis, through the expression of VEGF, HIF-1α, and MVD plays an important role supporting the aggressive nature of BRCA1-2 carrier cancers." (PMID 23326384, 2013). "In addition to HIF-1α, c-Met may co-facilitate cancer progression with HPV infection as well." (PMID 23927384, 2013). "Considering the important role of HIF-1α in the angiogenesis of tumors, HIF-1α is a target for cancer therapy." (PMID 24260057, 2013). "It seems that baicalein inhibited cancer cell viability through the inhibition of cancer promoting genes expression including VEGF, HIF-1α, cMyc, and NFkB." (PMID 23502466, 2013). "Our data show that novobiocin reduced selective HIF1α target gene mRNA, especially that of CA9 in several cancer cell lines." (PMID 23671581, 2013). "The stabilization of HIF-1α mediated the overexpression of VEGF, which has been identified as a common step in the development of carcinomas." (PMID 23997793, 2013). "The co-expression incidence of HIF-1α and HIF-2α was very low in head & neck (2%) and colon (3%) cancers compared to ccRCC (32%)." (PMID 22804960, 2012). "Staining of MUC1 (membrane), HIF1A (cytoplasm), and NKX2-1 (nucleus) classified cancer by subtype and cancer-free lung tissue with a failure rate of 11.0%." (PMID 23028920, 2012). "Importantly, we demonstrated that HIF-1α may regulate cancer cell migration through CX3CR1." (PMID 22952674, 2012). "IHC assessments in human cancer biopsies have found elevated levels of HIF-1α and/or HIF-2α protein in the majority of primary human cancers and their metastases." (PMID 22454562, 2012). "Together, these results point to the HIF-1α, mPGES-1 and PGE2 axis as a potential mediator of the anti-cancer effects of SFN, and illustrate the potential of SFN for therapeutic control of cancer and inflammation." (PMID 23166763, 2012). "It has previously been shown that conditional deletion of Hif1a in PyMT+ tumors by crosses to mice expressing MMTV-Cre delayed the onset of palpable tumors, delayed the progression of hyperplasias to carcinomas and reduced lung metastases." (PMID 22225988, 2012). "Three clear cell cancer lines (ES-2, TOV21G, and RMG1) were transfected with siRNA targeting HIF1 α (hypoxia) and ENO1 (glycolysis)." (PMID 21754983, 2011). "It is noteworthy that anti-cancer activity of BA is exerted by inhibiting angiogenesis via inhibition of binding of STAT3 and HIF-1α to the VEGF promoter in PC-3 cells." (PMID 21731766, 2011). "Our present study showed that triptolide enhanced the cellular accumulation of HIF-1α protein in SKOV-3, A549 and DU145 cancer cells at normoxia, hypoxia or CoCl2-mimic hypoxia." (PMID 20932347, 2010). "Altogether, these data show that the presence of oncogenic KRAS and both HIF-1α and HIF-2α in cancer cells lead to increased cardiolipin level and enhanced mitochondrial respiration efficiency." (PMID 21073737, 2010). "The hypoxia-inducible factors-1α and -2α (HIF-1α and HIF-2α) are activated in cancer due to dysregulated ras signaling." (PMID 21073737, 2010). "Global gene expression analyses of these cell lines reveal that HIF-1α and HIF-2α work together to modulate cancer metabolism and regulate genes signature overlapping with oncogenic KRAS." (PMID 21073737, 2010).
cancer (continued). "Although HIF-1α and VEGF were reported to be expressed in many types of cancers, few studies which investigate the clinical value of these factors in solid tumors, in particular, in human CRC, have yet been reported." (PMID 20003271, 2009). "The substitution of C to T at positions 1772 of the exon 12 of the HIF-1α gene further increase the transactivation capacity of the HIF-1α gene and thus promote the development of female specific cancers." (PMID 20035632, 2009). "Hypoxia-inducible factor 1 alpha (HIF-1α) and vascular endothelial growth factor (VEGF) are frequently overexpressed in numerous types of cancers and are known to be important regulators of angiogenesis." (PMID 20003271, 2009). "The expression of HIF-1α depends on FAK and phosphoinositide-3 kinase (PI-3) activation in cancer cells." (PMID 19919679, 2009). "Hypoxia, and particularly HIF-1α, has also been shown to regulate the expression of CXCR4 in cancer, including NSCLC." (PMID 19563666, 2009). "In cancer, the HIF system is up regulated both by microenvironmental hypoxia and by genetic events that lead to enhanced translation or stability of HIF-1α." (PMID 20003191, 2009). "Specifically, HIF-1α and the oncogene MYC, which is also a transcription factor, act in concert to "fine tune" cancer cells' adaptive responses to hypoxic environments." (PMID 19948069, 2009). "It was recently reported that 2-MeOE2, by disrupting microtubule stability, causes downregulation of the pro-angiogenic transcription factor Hif-1α in PC3 and MDA-MB-231 cancer cells with a subsequent reduction in VEGF production." (PMID 17426705, 2007). "LW6, an inhibitor of HIF-1α and a potential anti-cancer therapeutic, has not been previously evaluated in cartilage regeneration-related studies and chondrogenic cell sheet systems." (PMID 41514277, 2026). "After adjustments, the controls and cancer-affected tissue samples showed significantly higher HIF1A expression and slightly, but not significantly, higher VEGFA expression levels." (PMID 39888575, 2026). "In addition, by suppressing miR-155 and inhibiting hypoxia-inducible factor-1 alpha (HIF-1α), RA influences the IL-6/STAT3 pathway, reducing inflammation and encouraging cancer cell death." (PMID 40427522, 2025). "Inhibiting HIF-1α and HIF-2α is a potential cancer treatment strategy." (PMID 40305214, 2025). "Several studies have previously investigated the roles of CCND1, GABPA, HIF1A, and SOX6 in various diseases, including cancer and cardiovascular diseases, but the specific roles of these genes in HF and their interaction within the context of the PI3K/AKT pathway have not been well-explored." (PMID 40818967, 2025). "Simultaneously, activation of the small GTPase Ras plays a critical role in stabilizing HIF-1α, a transcription factor that promotes the expression of MMP-9 and fascin—a protein that bundles actin filaments and enhances cancer cell migration, dispersion, and invasion." (PMID 40322886, 2025). "Conjugated with a releasable cell-penetrating peptide tag, Transactivator of Transcription (TAT) peptide, Cyclo-C(TAT)LLFVY demonstrated selective binding to the PAS-B domain of HIF-1α, exhibiting a KD of 124 nM by ITC and effectively inhibited HIF-1 signaling in hypoxic MCF-7 and U2OS cancer cells." (PMID 39470609, 2025). "ChIP‐Seq and ChIP‐qPCR analysis allowed us to identify a subset of hypoxia‐regulated genes that are co‐occupied by both TFAP2A and HIF‐1α, both in HeLa and MCF7 cancer cell lines, providing evidence that binding of TFAP2A to HIF‐inducible promoters is not a cell type‐specific event." (PMID 39994865, 2025). "Furthermore, the interplay between hypoxia-inducible factor 1 alpha (HIF-1α) and B7-H3 has been observed, where HIF-1α upregulates B7-H3 expression under hypoxic conditions, contributing to the adaptation of cancer cells to low oxygen environments." (PMID 40230524, 2025).
cancer (continued). "Indeed, we found that 2-ANPC induced a moderate decrease in HIF-1α expression under hypoxic conditions, thereby revealing its impact on HIF-1α signaling in cancer cells." (PMID 41514626, 2025). "HIF-1α can induce VEGF overexpression and promote cancer progression." (PMID 40995093, 2025). "Although HIF1α is overexpressed in most types of cancer in humans, the role of this gene in cancer formation is not fully understood." (PMID 40917301, 2025). "Furthermore, our investigation revealed that UBE2S, HIF‐1α, and FOXM1 exhibited significant upregulation in both esophageal intraepithelial neoplasia and cancer, with statistically significant variations observed." (PMID 41427004, 2025). "Hypoxia induces cellular adaptation largely through hypoxia-inducible factors, particularly HIF-1α, which drive the transcription of genes involved in angiogenesis, metabolic reprogramming, and EMT, thereby enhancing cancer cell invasiveness and resistance to therapy." (PMID 41007281, 2025). "Importantly, ROS play a dual role in cancer biology: at moderate levels, they stimulate proliferation, angiogenesis, and metastasis by activating factors such as VEGF and HIF-1α, whereas excessive ROS levels can trigger cytotoxicity." (PMID 41303490, 2025). "Moreover, a correlation analysis revealed a significant positive correlation between HIF‐1α and CEPT1 expression in the cancer tissues of GC patients." (PMID 40954549, 2025). "Targeting HIF-1α and HIF-2α represents a promising therapeutic strategy for cancer." (PMID 40004471, 2025). "Thus, the MVP ribonucleoprotein complex was shown to inhibit cancer cell proliferation and survival via the inhibition of STAT3 signaling and enhancement of HIF1α." (PMID 40243914, 2025). "HCC patients with increased numbers of cancer stem cells also displayed an accumulation of a HIF-1α-driven SPP1+ macrophage subset characterized by the expression of MMPs (MMP9, MMP12, and MMP17), which may enhance cancer epithelial‒mesenchymal transition." (PMID 40721870, 2025). "Additionally, further exploration of the HIF-1α, LOX and ITGA5 axis in various cancer types and its therapeutic targeting will provide deeper insights into its roles in cancer progression and resistance to treatment." (PMID 39857068, 2025). "Finally, inhibition of the HIF-1α/SLC7A11 pathway blocks the Warburg effect and iron metabolism imbalance, inducing ferroptosis in cancer cells." (PMID 40584613, 2025). "Furthermore, paeonol inhibits cancer cell growth, proliferation, invasion and metastasis by inducing cell apoptosis and the suppression of the TLR4/NF-κB/STAT3/MAPK/PI3K/AKT/CHOP/VEGF/HIF-1α, pathways." (PMID 40083771, 2025). "Hypoxic cancer cells secrete cytokines (CCL26, G-CSF, IL-6) to attract MDSCs to the TME, where HIF-1α drives the expression of ENTPD2, an enzyme that plays a key role in purinergic signaling within the TME, ensuring their survival and maintenance within the TME." (PMID 39857427, 2025). "Conversely, disrupting the functional interplay between HIF-1α and SOD2 could render cancer cells more sensitive to oxidative stress, potentially improving the efficacy of therapeutic interventions." (PMID 39860164, 2025). "This supports the possibility that cancers can develop resistance to CXCR2 inhibition via the upregulation of HIF1A or MYC expression and suggest that combining drugs targeting CXCR2 and HIF1A or MYC may increase their therapeutic efficacy." (PMID 40050422, 2025). "HIF-1α stimulates EMT-TF activity and enhances cancer progression and chemotherapy resistance." (PMID 39941895, 2025). "Since drugs targeting CXCR2 have failed to prove effective in the clinic, we reasoned cancer cells expressing high levels of HIF1A or MYC are resistant to CXCR2 inhibitors." (PMID 40050422, 2025).
cancer (continued). "Therefore, the deviation of glucose to the PPP, orchestrated by factors like HIF-1α in the TME, is a critical mechanism by which cancer cells acquire hallmarks of malignancy, making HIF-1α and PPP enzymes promising targets for therapeutic intervention." (PMID 40963621, 2025). "Mechanically, we found that TZP exerted its anti‐CRC effect by inhibiting glucose influx and targeting HIF‐1α for degradation with reduced expression of its downstream glycolytic gene PFKFB3 and PFK‐1, leading to reduced glycolysis and TCA in the cancer tissues." (PMID 40125821, 2025). "These inflammatory responses activate transcription factors that are extensively involved in cancer development and progression, such as signal transducer and activator of transcription 3 (STAT3), hypoxia-inducible factor 1 alpha (HIF1α), and nuclear factor-κB (NF-kB)." (PMID 40806452, 2025). "Furthermore, cancer‐derived succinate activates SUCNR1 receptors on macrophages, polarizing them toward metastasis‐promoting states via the HIF‐1α and PI3K signaling cascades." (PMID 40904700, 2025). "Studies have found that HIF-1α could combine with HK2 promoter sites, raise the expression of HK2 to promote cancer cell to glucose metabolic reprogramming." (PMID 39991762, 2025). "Rg3 inhibits NF-κB and HIF-1α nuclear enrichment by eliminating GEM-induced ROS-mediated Akt activation and ERK signaling, thereby reducing GEM-induced ROS production and the migration and invasion of cancer cells." (PMID 41585262, 2025). "For example, HIF-1α promotes the proliferation of endothelial cells and tumor angiogenesis by mediating the VEGFR-1/VEGF/VEGFR-2 autocrine signaling pathway, which enhances the survival of cancer cells under hypoxic conditions." (PMID 40421268, 2025). "Gene set enrichment analysis (GSEA) also revealed a significant downregulation of the hypoxia pathway and HIF-1α target genes upon ASH1L depletion, particularly those involved in cancer cell invasion (Snail, TGFB, and MET), extracellular matrix remodeling (MMPs and PLAU), and angiogenesis (VEGFs)." (PMID 40394007, 2025). "Notably, macrophages have been shown to express HIF-1α, which requires LDHA activity in cancer cells." (PMID 40746883, 2025). "We hypothesized that nanoradiosensitizers with desired surface characteristics could be used to deliver small interfering RNA (siRNA) cocktails targeting survivin, HIF‐1α, and TGF‐β to improve RT efficacy by increasing radiosensitivity of cancer cells." (PMID 39535730, 2025). "Based on these data, it is proposed that RG6016 may modulate the HIF-1α pathway via LSD1, UCHL1, and MYC in aggressive cancers such as SCLC, thereby influencing key processes like hypoxia response, metastasis, and neuroendocrine differentiation." (PMID 40428124, 2025). "The roles of HIF-1α and SOD2 in cancer are context-dependent." (PMID 39860164, 2025). "PTMs of tight junction proteins, including epithelial cell adhesion molecule (EpCAM) and claudins, cytoskeletal proteins (vimentin, actins, and tubulins), HIF1α, EMT-TFs, and matrisome proteins (collagen, fibronectin, and metalloproteinases) modulate invasion and metastasis of cancer." (PMID 39860065, 2025). "Although oncogene activation (e.g., MYC and RAS) and hypoxia (HIF-1α stabilization) are acknowledged contributors, they do not fully explain the metabolic phenotype observed in all cancer types." (PMID 41158916, 2025). "MDA‐MB‐231 cells were treated with CNa 29 to determine whether pharmacological inhibition of calpain 2 by CNa 29 prevents filamin A cleavage‐induced HIF1α nuclear translocation, TWIST1 expression, EMT, cancer stemness, and metastasis." (PMID 40151834, 2025). "Moreover, there was a significant positive correlation between HIF‐1α and CEPT1 expression in the cancer tissues of GC patients." (PMID 40954549, 2025).